EHF (ETS homologous factor)
Diseases named in the same sentence as EHF in open-access papers (continued):
Sharing a sentence is not in itself a finding about the gene and the disease.
cancer (38 papers, 2007 to 2025). A tumor composed of atypical neoplastic, often pleomorphic cells that invade other tissues. "We therefore propose that EHF mutation was first discovered to promote cancer aggressiveness by promoting EMT." (PMID 33712555, 2021). "Functional assays demonstrated that ESE3/EHF repressed transcription of miR-424 in normal prostate epithelial cells and loss of ESE3/EHF triggered miR-424 upregulation in cancer cells." (PMID 31143708, 2019). "Therefore, we suggest that EHF acts as an anti-EMT factor by inhibiting the expression of ZEBs, and that EHF mutations exacerbate cancer progression." (PMID 33712555, 2021). "This analysis revealed that resistant cells upregulated transcription factors downstream of the ERBB signaling pathway including AP-1 components, FOS, FOSB, JUN, and JUND, and also SOX9 and EHF; all of which are known promoters of cancer proliferation." (PMID 40341770, 2025). "In recent years, dysregulation of EHF expression has been reported in various cancers; however, its specific mechanisms in different types of cancers have been inconsistent." (PMID 38741887, 2024). "Some studies showed that the overexpression of EHF protein plays a role in metastasis, proliferation, and shorter survival rates in cancer patients." (PMID 38308339, 2024). "E26 transformation‐specific homologous factor (EHF), a member of the E26 transformation‐specific transcription factor family, plays a pivotal role in epithelial cell differentiation and cancer progression." (PMID 38741887, 2024). "In these cases, demethylating agents led to the re-expression of EHF and suppressed cancer progression." (PMID 37958443, 2023). "In vivo metastasis was also repressed by EHF-SF, suggesting that EHF-SF ameliorates the exacerbation of cancer in vivo." (PMID 33712555, 2021). "A further mechanism of ESE transcription factor suppression in cancer is via promoter methylation, which has been reported for EHF in prostate and pancreatic cancer, and for ELF5 in bladder cancer." (PMID 30200227, 2018). "In contrast, EHF is negatively correlated with SLFN11 expression in other cancers from NCI60 and CCLE data sets." (PMID 28212573, 2017). "More recently, we have reported that ESE3/EHF controls the Lin28/let-7 axis acting as a critical barrier to malignant transformation and preventing cancer stem cell expansion." (PMID 27732936, 2016). "In this study, in an effort to further understand the mechanisms by which ESE3/EHF controls cancer stem-like cells we uncovered that IL-6 is a key target repressed by ESE3/EHF." (PMID 27732936, 2016). "We have previously reported that tumors with low levels of ESE3/EHF have aggressive clinical characteristics and are phenotypically associated with EMT and cancer stem cell features." (PMID 27732936, 2016). "Specifically, loss of ESE3/EHF leads to upregulation of IL-6 and activation of the JAK/STAT3 pathway with consequent induction of EMT and expansion of the cancer stem cell compartment." (PMID 27732936, 2016). "The highest ABC score (0.130) for this variant was with the ETS homologous factor gene (EHF), whose roles in cancer remain largely unknown." (PMID 38308339, 2024). "This evidence could explain the apparently contradictory data concerning the role of EHF in cancer progression." (PMID 35453848, 2022). "Notably, EHF mRNA levels in all four datasets were significantly lower in cancer tissues compared to normal tissues, which was correlated with overall survival." (PMID 33712555, 2021). "Compared to ELF3, mutations in EHF are relatively rare in human cancers and are not frequently deposited in public datasets." (PMID 33712555, 2021). "Mutations in EHF are relatively rare in human cancers and those which do arise are predominantly non-recurring missense mutations." (PMID 30200227, 2018).
cancer (continued). "ELF5 is located within close proximity of the related ESE member EHF on chromosome 11p13, and analysis of a panel of various cancer cell lines indicates that EHF and ELF5 are amplified or deleted in the same cases, making identification of the driver gene in these cases challenging." (PMID 30200227, 2018). "Moreover, EHF overexpression dramatically enhanced the growth and invasive abilities of cancer cells, further supporting its oncogenic function." (PMID 27517321, 2016). "This suggests that the subcellular location of EHF may determine the role of EHF in cancer cells." (PMID 37958443, 2023). "Likewise, mutations in ELF3 in many cancer tissues have also been deposited in the TCGA dataset, whereas those in EHF have not." (PMID 33712555, 2021). "Importantly, mutations within the conserved ETS domain in EHF and ELF3 abolish the ability of these proteins to inhibit EMT, and this subsequently promotes tumor growth and invasion in vivo, leading to a dominant negative fashion on EMT and cancer cell differentiation in vivo." (PMID 39362647, 2024). "However, what determines the function of EHF in various cancers remains unclear." (PMID 37958443, 2023). "EHF and ELF3 play important roles as cancer‐promoting TFs in various cancers, their involvement in HRR has not been reported." (PMID 37702443, 2023). "Our pan-cancer analyses from TCGA revealed that aberrant expressions of ELF3, EHF, and TGIF1 are prevalent in a wide spectrum of cancers and high levels of these master TFs are associated with poor patient outcomes." (PMID 33070167, 2020). "To examine if ELF3, EHF and TGIF1 levels are important in human cancers, we measured mRNA expression of these in LUAD tissues along with their paired adjacent peritumoral tissues." (PMID 33070167, 2020). "Taken together, our study unveiled a novel miR-365-3p/EHF/KRT16/β5-integrin/c-Met signaling axis regulating metastasis, cancer stemness, and drug resistance in OSCC." (PMID 30782177, 2019). "Conversely, ectopic expression of EHF in MGC803 cells significantly enhanced the migration and invasive potential of cancer cells." (PMID 27787520, 2016). "This establishes a novel IR-JMJD6-EHF signaling axis in EHF, once transcriptionally activated by JMJD6, acts as a pioneer factor that opens up chromatin and facilitates the expression of a broader network of genes involved in cancer cell stemness and survival." (PMID 41320721, 2025). "Furthermore, we unveiled the novel miR-365-3p/EHF/KRT16/β5-integrin/c-Met pathway capable of regulating OSCC cell migration, invasion, metastasis, and cancer stemness by activation of the Src/STAT3 signaling." (PMID 30782177, 2019). "Moreover, several transcriptional factors, such as NF-κB, c-myc and β-catenin, can activate LIN28 and repress let-7 expression to augment cancer progression, while REST and ESE3/EHF are transcriptional repressors of LIN28." (PMID 30016974, 2018). "Relevantly, we have recently shown that ESE3/EHF directly controls the level and activity of distinct components of the Lin28/let-7 axis, a key pathway involved in stem cell biology and expansion of cancer stem cell compartment." (PMID 27732936, 2016). "For example, PLEC, ANXA10, EHF, SLC4A, and CUL4A are expressed at high levels in MDA-MB-231 relative to MCF-7 cells, and MAGED1, SYK, and EPCAM are expressed at higher levels in triple-negative cancer tissues relative to non-invasive control tissues." (PMID 26053433, 2015). "Interestingly, these TFs, together with OVOL1/2 (Ovo Like Transcriptional Repressors 1 and 2), had previously been suspected to inhibit epithelial–mesenchymal transition in cancer cells with a hierarchically dominant position for GRHL2, which directly induces expression of EHF and OVOL2." (PMID 41385584, 2025).
cancer (continued). "Some downregulated genes (EHF and MMP14), mainly involved in proliferation and cancer development, were not restored upon EZH2 inhibitor treatment, and some that were upregulated in KO samples retained or even increased their high expression after treatment (EFCAB6 and CDKN2A)." (PMID 38672463, 2024). "Therefore, EHF, rather than ELF3, would be very involved in cancer progression in HNSCC." (PMID 33712555, 2021).
EHF also shares sentences with these, for which no sentence is quoted: infection (3 papers); gastric adenocarcinoma (2); head and neck cancer (2); adenocarcinoma (1); ampullary carcinoma (1); colon cancer (1); esophageal cancer (1); head and neck squamous cell carcinoma (1); leukemia (1); lung adenocarcinoma (1); metastatic cancers (1); neuroblastoma (1); non-small cell lung carcinoma (1); prostate adenocarcinoma (1); renal carcinoma (1); spinal muscular atrophy (1); steatosis (1).